STK38L (serine/threonine kinase 38 like)
Description:
Involved in the regulation of structural processes in differentiating and mature neuronal cells.
Synonyms: KIAA0965; NDR2
Tractability: Small molecule: a high-quality ligand is known; it belongs to a druggable protein family. PROTAC: ubiquitination databases record sites on it; its protein half-life has been measured; a small molecule that binds it is known.
Target class: Kinase; Enzyme; Protein Kinase; AGC protein kinase group; AGC protein kinase NDR family
Gene: Protein-coding gene on chromosome 12 (27,243,968 to 27,325,959, forward strand). Ensembl gene ENSG00000211455.
Subcellular location: Cytoplasm; Cytoplasm, cytoskeleton; Membrane
Subcellular location (Human Protein Atlas): Cytosol
Gene Ontology:
Molecular function: ATP binding; magnesium ion binding; protein binding; protein serine/threonine kinase activity; protein kinase activity; protein serine kinase activity
Biological process: intracellular signal transduction; negative regulation of autophagy; protein phosphorylation; regulation of cellular component organization
Cellular component: cytoplasm; cytosol; actin cytoskeleton; cytoskeleton; membrane
Genetic constraint (gnomAD): Loss-of-function variants: 21 observed, 44.28 expected, observed/expected ratio (o/e) 0.47, 90% interval 0.34 to 0.68. The upper end of that interval is the gene's LOEUF score, 0.68, which puts it in group 2 of 6, group 1 being the genes least tolerant of losing a copy. Missense variants: 262 observed, 474.7 expected, observed/expected ratio (o/e) 0.55, 90% interval 0.5 to 0.61. Synonymous variants: 145 observed, 155.21 expected, observed/expected ratio (o/e) 0.93, 90% interval 0.81 to 1.07.
Homologues: Orthologues: chimpanzee STK38L (100% identical), dog STK38L (99% identical), pig STK38L (99% identical), mouse Stk38l (98% identical), rat Stk38l (98% identical), macaque STK38L (93% identical), tropical clawed frog stk38l (91% identical), zebrafish stk38l (90% identical), rabbit STK38L (88% identical), Drosophila melanogaster trc (68% identical), Caenorhabditis elegans sax-1 (65% identical). Paralogues in human: STK38 (87% identical).
Diseases named in the same sentence as STK38L in open-access papers:
STK38L is named in the same sentence as 44 diseases in open-access papers, as found by Europe PMC text mining. Sharing a sentence is not in itself a finding about the gene and the disease. The quoted sentences say what the papers report.
retinal degeneration (11 papers, 2013 to 2025). Degeneration of the retina. "STK38L/NDR2 is involved in primary cilium formation and is mutated in a naturally occurring canine ciliopathy, termed early retinal degeneration." (PMID 38523660, 2024). "There are, however, inherited diseases that have been reported to be caused by SINE insertions, including an intronic SINE in FAM161A that is associated with PRA in Tibetan Terriers and Tibetan Spaniels and an exonic SINE in STK38L that causes early retinal degeneration in Norwegian Eklhounds." (PMID 39062732, 2024). "Similarly, early retinal degeneration cosegregates with an exonic SINE insertion in exon 4 of STK38L gene causing loss of the N terminus of the translated protein." (PMID 33494213, 2021). "SINE elements were also shown to cause several inherited diseases, like recessive centronuclear myopathy in Labrador Retrievers and early canine retinal degeneration, which was linked to the serine/threonine kinase 38 like (STK38L) gene in Norwegian Elkhound–Beagle outcrosses by linkage mapping." (PMID 31681409, 2019). "Mitotic terminally differentiated photoreceptors (PRs) are observed in early retinal degeneration (erd), an inherited canine retinal disease driven by mutations in the NDR kinase STK38L (NDR2)." (PMID 26969498, 2016).
lung carcinoma (7 papers, 2015 to 2025). "In contrast, STK38L knockdown failed to induce apoptosis in a KRAS mutant lung cancer cell line H358." (PMID 29108249, 2017).
ciliopathy (4 papers, 2016 to 2025). A genetic disorder of the cellular cilia or the cilia anchoring structures, the basal bodies, or of ciliary function. "We identified 10 genes (STK38L, TUBB2A/B, CCNO, ARL13B, RFX2, RAB23, TUBA1C, CEP170B, and SPATA7) that are established or candidate ciliopathy genes." (PMID 34485842, 2021).
colon cancer (2 papers, 2015 to 2017). "We previously identified non-oncogene dependency for the nuclear Dbf2 and LATS1/2-related kinase STK38L (also known as NDR2) in the KRAS-mutant SW620 colon cancer cell line." (PMID 29108249, 2017).
glioma (2 papers, 2022 to 2025). A benign or malignant brain and spinal cord tumor that arises from glial cells (astrocytes, oligodendrocytes, ependymal cells). "For the 3 East Asian GWAS-identified risk loci (i.e., 12p11.23, 15q15-21.1, and 19p13.12), the risk SNP (i.e., rs10842893) located on 12p11.23 was in the intronic region of the gene STK38L, and the expression of STK38L was higher in the glioma samples than the normal samples in TCGA database." (PMID 36350002, 2022).
Intellectual disability (2 papers, 2023 to 2025). "The human NDR2 gene (STK38l) has been identified as a susceptibility gene for neurodevelopmental disorders, intellectual disability, and autism spectrum disorder." (PMID 40439020, 2025). "Furthermore, seven intellectual disability candidate genes, TM7SF3, STK38L, ARNTL2, ERGIC2, TMTC1, DENND5B and ETFBKMT have been identified." (PMID 37034680, 2023).
pancreatic cancer (2 papers, 2017 to 2018). "It has been reported that downregulation of lncRNA metastasis associated lung adenocarcinoma transcript 1 (MALAT1) and serine/threonine kinase 38 like (STK38L) lead to the accumulation of LATS1 and decrease the level of cellular YAP in pancreatic cancer cells." (PMID 30486435, 2018).
atrial fibrillation (1 paper, 2025). A disorder characterized by an electrocardiographic finding of a supraventricular arrhythmia characterized by the replacement of consistent P waves by rapid oscillations or fibrillatory waves that vary in size, shape and timing and are accompanied by an irregular ventricular response. "It was shown that STK38L (serine/threonine kinase 38 like) gene product promotes cardiac fibroblast activation and proliferation, and its increased expression is closely associated with atrial fibrillation characterized by atrial fibrosis and TGF-β1-induced myocardial fibrosis." (PMID 41153660, 2025).
breast carcinoma (1 paper, 2021). "The lncRNAs may act as competing endogenous RNAs (ceRNAs) and interfere in the binding of miR-190b to certain targets such as ERG, STK38L, and FNDC3A and thus contribute to breast cancer pathogenesis." (PMID 33976257, 2021).
Kallmann syndrome (1 paper, 2025). Kallmann syndrome (KS) is a developmental genetic disorder characterized by the association of congenital hypogonadotropic hypogonadism (CHH) due to gonadotropin-releasing hormone (GnRH) deficiency, and anosmia or hyposmia (with hypoplasia or aplasia of the olfactory bulbs). "Additionally, STK38l is situated within a cryptic translocation site found in patients with Kallmann syndrome, and the ECM molecule ANOSMIN‐1, produced by the KAL1 gene, has been demonstrated to activate β1 integrins." (PMID 40439020, 2025).
pancreatic adenocarcinoma (1 paper, 2017). "To assess the prevalence of STK38L gene copy number alterations in human PDAC, we analyzed the pancreatic adenocarcinoma (PAAD) dataset from The Cancer Genome Atlas (TCGA)." (PMID 29108249, 2017).
thyroid cancer (1 paper, 2019). "The phosphorylation of protein STK38L could cause mutation to promote cancer cell proliferation and destruct the core signaling transduction pathway in early-stage thyroid cancer cells." (PMID 31126066, 2019). "In addition, the mutation of the phosphorylation site of signaling transduction protein STK38L could ablate the kinase activity and block the activation, promoting cancer cell proliferation and destructing core pathway signaling transduction in the transforming early-stage thyroid cancer cells." (PMID 31126066, 2019).
cancer (10 papers, 2016 to 2025). A tumor composed of atypical neoplastic, often pleomorphic cells that invade other tissues. "STK38L, in turn, exhibited altered interaction with several interaction partners, of which many have been previously linked to cancer." (PMID 30108113, 2018). "If an association between HEY1 phosphorylation status and the cancer phenotype can be found, STK38, STK38L and other serine/threonine kinases responsible for the phosphorylation of HEY1 at Ser-68 may represent novel attractive targets for therapeutic intervention." (PMID 27129302, 2016).
tumor (8 papers, 2015 to 2025). "STK38/STK38L kinases phosphorylate the transcriptional coactivator yes-associated protein (YAP1) and thereby negatively regulate YAP1 transcriptional activity, suggesting that STK38/STK38L function as tumor suppressors." (PMID 37046714, 2023). "STK38L-mediated tumor suppression can occur via promotion of YAP phosphorylation and regulation of the Hippo signaling pathway." (PMID 29108249, 2017). "Previous studies demonstrate that STK38 and STK38L have redundant tumor suppressor function." (PMID 29108249, 2017). "Thus, it will be important to develop ATP-competitive inhibitors to validate the kinase-dependent functions of STK38L in normal cells and in the pathophysiological context of STK38L-dependent tumor cell survival." (PMID 29108249, 2017). "To elucidate mechanisms underlying STK38L dependency in PDAC cell lines, we characterized the effects of STK38L depletion on expression levels of key proteins in KRAS and general tumor-associated signaling pathways including p21, MYC, MAPK, PI3K, and autophagy." (PMID 29108249, 2017). "STK38L protein levels varied significantly across the primary tumor cohort." (PMID 29108249, 2017). "STK38L can play context-dependent, oncogenic or tumor suppressive roles." (PMID 29108249, 2017). "Further characterization of the mechanistic relationship between STK38L and KRAS will be critical to fully understand context-dependent tumor cell survival signaling networks in KRAS mutant PDACs." (PMID 29108249, 2017). "We conclude that STK38L and KRAS gene copy number, mRNA, and protein levels are tightly correlated in human PDAC and tumor-derived cell lines." (PMID 29108249, 2017). "Therefore, we conclude that STK38L and KRAS function in parallel pathways to promote tumor cell survival." (PMID 29108249, 2017).
neurodevelopmental disorder (3 papers, 2023 to 2025). A behavioral and cognitive disorder with onset during the developmental period that involves impaired or aberrant development of intellectual, motor, or social functions. "Putative position effect of TM7SF3 and the inclusion of STK38L and ARNTL2 in CNVs at 12p11.23 along with their sporadic variants reported in neurodevelopmental disorder (NDD) patients will likely explain their candidacy." (PMID 37034680, 2023). "As a result, we identified a dozen candidate genes: TSPAN11 as a potential KS candidate gene, TM7SF3, STK38L, ARNTL2, ERGIC2, TMTC1, DENND5B, and ETFBKMT as candidate genes for the neurodevelopmental disorder, and INTS13, REP15, PPFIBP1, and FAR2 as candidate genes for KS with ID." (PMID 37563198, 2023). "The results identified one potential KS candidate gene (TSPAN11), seven candidate genes for the neurodevelopmental disorder (TM7SF3, STK38L, ARNTL2, ERGIC2, TMTC1, DENND5B, and ETFBKMT), and four candidate genes for KS with ID (INTS13, REP15, PPFIBP1, and FAR2)." (PMID 37034680, 2023).
STK38L also shares sentences with these, for which no sentence is quoted: non-small cell lung carcinoma (3 papers); retinal diseases (3); Alzheimer disease (2); centronuclear myopathy (2); adenocarcinoma (1); age-related macular degeneration (1); amyloidosis (1); Anxiety (1); autism (1); autism spectrum disorder (1); Blindness (1); brain disorder (1); colon (1); colorectal cancer (1); cyclopia (1); diabetic retinopathy (1); Hyperglycemia (1); Leber congenital amaurosis (1); lung adenocarcinoma (1); metabolic disease (1); metastatic cancer (1); Myocardial fibrosis (1); neurodegenerative disease (1); osteoporosis (1); ovarian carcinoma (1); pancreatic ductal adenocarcinoma (1); Parkinson’s (1); retinopathies (1); sexual (1).